RNU6-403P (RNA, U6 small nuclear 403, pseudogene)
Gene: Small nuclear RNA gene on chromosome 1 (221,837,334 to 221,837,437, reverse strand). Ensembl gene ENSG00000200033.
Homologues: Orthologues: chimpanzee U6 (98% identical), macaque U6 (94% identical), mouse Gm25512 (84% identical), tropical clawed frog U6 (83% identical), guinea pig U6 (81% identical). Paralogues in human: RNU6-1124P (91% identical), RNU6-140P (90% identical), RNU6-24P (90% identical), RNU6-29P (90% identical), RNU6-338P (90% identical), RNU6-732P (90% identical), RNU6-12P (89% identical), RNU6-13P (89% identical), RNU6-25P (89% identical), RNU6-32P (89% identical), RNU6-33P (89% identical), RNU6-41P (89% identical), and 1284 more.